LINC02516 (long independently transcribed non-coding RNA 2516)
Gene: Long non-coding RNA gene on chromosome 4 (124,499,937 to 124,641,930, reverse strand). Ensembl gene ENSG00000261083.
Diseases named in the same sentence as LINC02516 in open-access papers:
LINC02516 is named in the same sentence as 1 disease in open-access papers, as found by Europe PMC text mining. Sharing a sentence is not in itself a finding about the gene and the disease. The quoted sentences say what the papers report.
colon cancer (1 paper, 2021). "The molecular colon cancer overall prognosis prediction model contains 6 molecules (AC004080, AP000842, LINC02516, hsa-mir-891a, cg04727865, cg14234213)." (PMID 34095132, 2021).